POMC (proopiomelanocortin)
Diseases named in the same sentence as POMC in open-access papers (continued):
Sharing a sentence is not in itself a finding about the gene and the disease.
Obesity (continued). "Furthermore, enhancing melanocortin signaling through overexpression of MC4R, POMC, or its derived peptides showed limited effects on obesity prevention or reversal." (PMID 40130157, 2025). "Thus, early genetic studies of severe obesity (SevO) focused on identifying gene-disrupting mutations in the leptin-melanocortin pathway (e.g., LEPR, MC4R, POMC), which are linked to early-onset SevO through dysregulation of food intake and food preferences." (PMID 40939575, 2025). "These obesity-related changes may include alterations in the leptin hormone which can stimulate POMC-expressing neurons and subsequently affect MC4R stimulation." (PMID 39542230, 2025). "Interestingly, semaphorins are also important players in monogenic obesity being involved in neuronal projection of pro-opiomelanocortin (POMC) neurons and thereby, contributing to neuronal circuitry in the leptin-melanocortin pathway." (PMID 41225618, 2025). "Notably, microglia-specific UCP2 knockout mitigates HFD-induced neuroinflammation by suppressing these cytokine cascades, thereby restoring POMC neuron function and reducing obesity." (PMID 40452923, 2025). "While monogenic nonsyndromic obesity (such as mutations in the MC4R, LEP, or POMC genes) generally presents with severe hyperphagia and weight gain in early life but otherwise normal neurocognitive development, syndromic forms typically display additional systemic or neurological features." (PMID 40689079, 2025). "Therefore, our findings suggest that cPLA2-regulated PG synthesis in the VMH is essential for feeding termination via POMC neurons, as its knockdown resulted in hyperphagia and subsequent obesity." (PMID 40806659, 2025). "The alteration of certain obesity-promoting genes (e.g., FTO and peroxisome proliferator-activated receptor gamma gene (PPARγ)) and anti-obesity genes (e.g., LEP, GLP-1R, and POMC) may be associated with obesity." (PMID 40868241, 2025). "Similarly, other components of the leptin–melanocortin axis, including LEP, LEPR, POMC, PCSK1, and SIM1, have been associated with both monogenic and polygenic obesity." (PMID 41226372, 2025). "Following maternal undernutrition, the development of obesity in the offspring may be related to decreased POMC neuronal function since birth." (PMID 40474775, 2025). "Understanding these novel mutations in POMC and MC4R/MC3R, as well as their structural and intracellular mechanisms, may help identify strategies for the treatment and diagnosis of obesity, particularly childhood obesity." (PMID 40001512, 2025). "The hypothalamic POMC neurons have been reported involved in age-dependent obesity." (PMID 41037185, 2025). "Important genes associated with monogenic obesity consist of leptin (LEP), leptin receptor (LEPR), proopiomelanocortin (POMC), prohormone convertase 1 (PCSK1), MC4R, single-minded homolog 1 (SIM1), brain-derived neurotrophic factor (BDNF), and its receptor NTRK2 (commonly referred to as TrkB)." (PMID 40428329, 2025). "Therefore, enhanced POMC neuronal activity and decreased inflammation in the hypothalamus of Pdgfrb∆SYS-KO were observed independently of obesity-associated chronic inflammation in adipose tissue." (PMID 38317079, 2024). "Lastly, we interrogated whether obesity affects the effects of the coordinated reciprocal interplay between AgRP and POMC neurocircuits in the regulation of feeding and metabolism." (PMID 38378998, 2024). "Additionally, obesity-induced hypertension is attributed to the direct enzyme activation in POMC neurons located in the mediobasal hypothalamus." (PMID 38892653, 2024). "Finally, in contrast to anorexigenic POMC neurons, a BNC2-specific knockout of LepR causes significant hyperphagia and obesity." (PMID 39478220, 2024). "Importantly, even under normal diet conditions, specific p62 knockout in POMC neurons induced a significant obesity phenotype." (PMID 39479445, 2024).
Obesity (continued). "Early studies mainly explored obesity-causing genes from a single-gene perspective, and >20 causative genes have been confirmed to be highly associated with the development of obesity, including FTO, PPARG2, LEP, MC4R, and POMC." (PMID 39389470, 2024). "The novel aspect of the proposed work lies in undertaking the issue of obesity pathogenesis by examining the secreted neuropeptides and neurotransmitters of pathologically relevant POMC neurons, the central control unit for organismal energy homeostasis and energy expenditure." (PMID 39329749, 2024). "In addition, other sirtuins, such as SIRT3 and SIRT6, have been shown to operate at the hypothalamic, and particularly in POMC neurons, to contribute to energy homeostasis and adaptive responses to lessen the metabolic impact of obesity." (PMID 39290326, 2024). "In mice, POMC-specific ASB4 knockdown resulted in impaired glucose tolerance without obesity, while overexpressing ASB4 in POMC neurons caused an increase in food intake without obesity." (PMID 39201703, 2024). "Understanding the exact mechanism which leads to metabolic alterations in POMC neurons by excessive and/or oxidized fatty acids may help us develop strategies for the prevention and treatment of obesity and related lifestyle-related diseases." (PMID 39683565, 2024). "In young mice with global deletion of HDAC5, the exposure to HFD led to impaired expression of the anorexigenic neuropeptide proopiomelanocortin (POMC) that translated into leptin resistance, elevated food consumption and diet-induced obesity, compared to HFD-fed wildtype controls." (PMID 39304061, 2024). "Since proopiomelanocortin (POMC) neurons in the hypothalamus are related to the control of appetite and energy expenditure, their cell degeneration/death is crucial for the occurrence of obesity." (PMID 39683565, 2024). "We also emphasize that the POMC gene not only influences feeding behavior but also may play a role in obesity-related hypothalamic inflammation." (PMID 39484290, 2024). "In this study, we identified a number of POMC-driven pathologically relevant secreted molecules that we believe could be targeted individually or in combination to combat obesity and related diseases." (PMID 39329749, 2024). "However, our findings challenge the traditional viewpoint that both environmental and genetic factors jointly contribute to obesity, emphasizing the important role of p62 in POMC neurons leading to obesity." (PMID 39479445, 2024). "Deletion of STAT in POMC neurons, which have a response element to this factor in their promoter, does not completely abolish leptin effects and causes only mild obesity." (PMID 36674935, 2023). "In addition, loss-of-function mutations of the gene CPE (4q32.3) can inhibit the cleavage of POMC into melanocortins, resulting in a triad composed of severe obesity, developmental delay, and hypogonadotropic hypogonadism." (PMID 37512517, 2023). "The most frequent causes of monogenic obesity are mutations in the genes leptin (LEP), leptin receptor (LEPR), melanocortin 4 receptor (MC4R), proopiomelanocortin (POMC), proprotein convertase subtilisin/kexin type 1 (PCSK1), and neurotrophic receptor tyrosine kinase 2 (NTRK2)." (PMID 37375898, 2023). "These cells play a key role in the control of food intake and energy balance, and the disruption of this circuit by changes in leptin sensitivity or mutations in the genes encoding leptin, the leptin receptor, POMC, or MC4R, amongst other genes in this system, can lead to severe obesity." (PMID 36674935, 2023). "In patients with obesity due to BBS, POMC deficiency, or LEPR deficiency, hyperphagia is associated with impaired health-related quality of life (HRQOL), with patients reporting guilt, frustration, sadness, and feelings of failure given the inability to control their hunger." (PMID 36647077, 2023).
Obesity (continued). "Further, an overstimulation of the endocannabinoid system in dietary fat-induced obesity may also contribute to diminished leptin response in POMC neurons." (PMID 37571301, 2023). "Overall, the study concluded that heterozygous variants involving PCSK1, POMC, LEP, and LEPR are common among adult patients with class III obesity and occasionally may exhibit a phenotype similar to that of homozygotes." (PMID 37835041, 2023). "Congenital targeting of Rpgrip1l in POMC neurons results in decreased neuronal number and obesity, while adult onset of hypomorphic mutations does not cause adiposity." (PMID 37064917, 2023). "Furthermore, gain of function of the melanocortin action through overexpression of MC4R, POMC or its derived peptides had little effect on obesity prevention or reversal." (PMID 37069175, 2023). "CK1α conditional deletion in mouse POMC neurons caused a decrease in their numbers and an increase in NICD protein levels, which subsequently resulted in a decrease in α-MSH peptide expression, eventually leading to obesity in PKO mice." (PMID 37168577, 2023). "SIRT1 in POMC neurons is required for normal adaptations against diet-induced obesity." (PMID 37886966, 2023). "This work suggests that maternal hyperglycemia produced by STZ treatment, in combination with early life exposure to an obesogenic diet leads to adult behavioral and metabolic alterations that correlate with increased expression of hypothalamic POMC to promote obesity." (PMID 37396180, 2023). "Thus, chronic inhibition of POMC neurons leads to massive obesity in both males and females, which is mainly attributed to hyperphagia." (PMID 37069175, 2023). "Studies have shown that POMC-specific deletion of Src1, a co-activator that enhances pSTAT3 transcriptional activity following leptin treatment, causes hyperphagia and obesity only when mice are fed with a HFD but not chow diet." (PMID 38027481, 2023). "Disruption of key genes in POMC neurons in female mice resulted in the development of obesity." (PMID 37443835, 2023). "Our observation that inhibiting CerS6-dependent ceramide synthesis in SF-1 and POMC neurons improves glucose homeostasis during HFD feeding, particularly in male mice, underscores the critical role of CerS6-derived ceramides in obesity-associated ER stress in these types of neurons." (PMID 38016943, 2023). "The retained higher ratios of the NPY to POMC neurons born during E12.5 in males may set a tone for male HFD offspring being prone to obesity development in later life." (PMID 37867217, 2023). "Monogenic obesity is caused by variants of only one gene, and several genes have been associated with this type of obesity, such as leptin (LEP), leptin receptor (LEPR), pro-opiomelanocortin (POMC), and melanocortin 4 receptor gene (MC4R), which is the most common form of monogenic obesity." (PMID 38003013, 2023). "In light of these observations, the induction of mild mitochondrial stress in POMC neurons may serve as a strategy to treat HFD-induced obesity." (PMID 39871928, 2022). "At the same time, cell-autonomous dysregulation of the Nras-insulin-PI3K-Akt axis within the POMC neurons may contribute to chronic impairment of anorexigenic signaling to the secondary regions culminating in the onset of hyperphagia and obesity." (PMID 35490865, 2022). "We observed no changes in POMC neurons in females, while there was a significant loss of POMC neurons in microglia-InsR-KO male mice, compared to microglia-InsR-Ctrl in obesity." (PMID 35328354, 2022). "Only male but not female mice with POMC-specific loss of PKCλ developed HFD-induced obesity and glucose intolerance." (PMID 36120438, 2022). "In support of this hypothesis, microglia-specific deletion of UCP2, a critical protein in mitochondrial function, prevents HFD-induced obesity and induces cytological markers of increased POMC neuronal activity." (PMID 35742824, 2022).
Obesity (continued). "In turn, mitochondrial dysfunction in POMC neurons leads to hyperphagia, the reduction of alpha-melanocyte stimulating hormone, attenuated lipolysis in white adipose tissue (WAT) and, finally, might cause obesity." (PMID 39871928, 2022). "Furthermore, we found life-long Pcsk1 knockout in POMC neurons to induce obesity which resolved after 6 and 12 months of age in male and female mice, respectively." (PMID 35963866, 2022). "However, in our case patients, the location of this POMC variant, together with the high ACTH levels, strongly suggests that their obesity and hyperphagia were indeed the consequence of impaired PC2 cleavage and thereby impaired activation of MC4R." (PMID 35737586, 2022). "Furthermore, the combined deletion of PTP1B and TCPTP in neuronal and glial cells or POMC neurons results in an improvement in leptin sensitivity as well as a decrease in diet-induced obesity." (PMID 35563589, 2022). "Early-onset severe obesity with hyperphagia is a hallmark phenotype associated with defective POMC, following the lack of POMC processing to α-MSH, d-α-MSH, and β-MSH, the most important ligands of the MC4R in the hypothalamus." (PMID 35737586, 2022). "As a result of these studies, patients with severe obesity and rare SRC-1 variants are now being recruited into phase 2 clinical trials of setmelanotide, an MC4R agonist, licensed for the chronic weight management of POMC and leptin receptor deficiency." (PMID 35137184, 2022). "Importantly, deletion of UCP2 in microglia is also associated with more excitatory synaptic inputs onto the POMC neurons, and this leads to increased sensitivity to leptin in POMC neurons and resistance to HFD-induced obesity in mice." (PMID 33826123, 2022). "Errors in the cleavage of master proteins such as POMC require pro-hormone convertase, which cleaves this large protein into smaller functional peptides and as noted, interacts with appetite control, pigment, and obesity." (PMID 36232301, 2022). "Furthermore, hypothalamic POMC neuron-specific ATF4 knockout protects DIO mice from obesity by increasing BAT thermogenesis and increasing oxygen consumption." (PMID 36188456, 2022). "Future studies on the function of AT2R in POMC neurons could provide a new approach to improve both metabolic and cardiovascular functions in obesity." (PMID 35807782, 2022). "The compound heterozygous carriers of pathogenic genetic variants in the autosomal recessive genes LEP, LEPR, POMC and PCSK1 are rare, obesity-associated variants in the autosomal dominant gene MC4R are the most common, with 0.8% of participants in our study carrying a variant in MC4R." (PMID 35574020, 2022). "Thus, mice that lack Nrp-2 in POMC-expressing neurons exhibit obesity and reduced energy expenditure due to disrupted arcuate POMC axonal projections to the PVH." (PMID 35045890, 2022). "Deletion of Tap63 in POMC neurons does not affect male body weight but renders females more susceptible to diet-induced obesity." (PMID 33826123, 2022). "A recent study showed that inhibition of ciliogenesis in developing POMC neurons, which was realized by depleting Kif3a or Ift88, led to adulthood obesity in mice; these mice showed disruption of axonal projections through impaired lysosomal protein degradation in POMC neurons." (PMID 34211092, 2021). "In mammals, loss of the genes encoding POMC or MC4R leads to severe obesity." (PMID 34440144, 2021). "Importantly, we previously showed that selective deletion of ERα from POMC-lineage neurons in female mice results in hyperphagia and obesity, and attenuates estrogen-induced anorexia." (PMID 34393830, 2021). "The stimulation of ARC POMC neurons caused by PACAP administered directly into the ARC suppresses energy intake and enhances energy metabolism, and these effects were markedly attenuated under conditions of diet-induced obesity." (PMID 33800452, 2021).
Obesity (continued). "However, knockdown of miR-7 in POMC neurons of female mice exacerbated diet-induced obesity, suggesting that the neuronal subtype and sex differences play an important role in the function of miR-7." (PMID 34831343, 2021). "However, we are unaware of any possible role of FTO associated with hair growth, although a previous study showed the possible role of POMC in severe early‐onset obesity in humans." (PMID 33410284, 2021). "However, overexpression of an anti-inflammatory cytokine-IL-10 in mice ameliorates HFD induced-obesity, restores POMC expression, and attenuates the leptin resistance by inhibiting IKKs activation and SOCS3 expression in ARC." (PMID 34720877, 2021). "Selectively knocking out 5‐HT2CRs only in POMC neurones does not promote obesity, but does cause hyperinsulinaemia, hyperglycaemia, hyperglucagonaemia and insulin resistance." (PMID 33909316, 2021). "Moreover, optimum POMC neuron stimulation by leptin requires the presence of EPOR and ΔEPORE mice show lower POMC expression, contributing to the obesity, insulin resistance, and glucose intolerance seen in these mice." (PMID 34603036, 2021). "Mice with ablation of FoxO1 in the POMC neurons are resistant to diet-induced obesity." (PMID 33849593, 2021). "Additionally, the hypothalamus of obese subjects was also found to be characterised by the presence of oxidative stress, which leads to the depletion of POMC neurons, and, consequently, to the induction of systemic leptin resistance and obesity." (PMID 34208585, 2021). "Hypothalamic inflammation affects both NPY and POMC and promotes obesity." (PMID 34307371, 2021). "Our results show that α-MSH is a key regulator of POMC signaling in appetite regulation and energy expenditure, suggesting that it might be a potential therapeutic target for treating human obesity." (PMID 34440144, 2021). "The melanocortin pathway which is linked to both melanin synthesis and obesity seems to be altered with unclear significance, as the sex difference in POMC, DCT/TYRP2, and MRAP2 was observed but with no clear direction." (PMID 34436011, 2021). "Additionally, leptin’s effects on obesity and insulin resistance are mediated by pro-opiomelanocortin (POMC)." (PMID 32131811, 2020). "A number of obesity-associated genes have been identified in adipogenesis regulation, such as melanocortin-4 receptor (MC4R), uncoupling protein-1 (UCP1), and pro-opiomelanocortin (POMC)." (PMID 33425901, 2020). "Mutations in POMC and MC4R genes lead to severe obesity due to hyperphagia." (PMID 32982666, 2020). "How does obesity amplify the actions of insulin (and leptin) on POMC neurons in males?" (PMID 32160920, 2020). "Similarly, ROCK1 deletion in POMC neurons leads to POMC hypoactivity and obesity due to reduced locomotor activity, while whole-ARC ROCK1 deletion has even greater effects." (PMID 33633690, 2020). "Moreover, genetic manipulation of the UPR transcription factor spliced X-box binding protein (Xbp1) specifically in POMC neurons protects against diet-induced obesity and ameliorates leptin and insulin sensitivity." (PMID 32163401, 2020). "Candidate obesity genes and traits associated with obesity include LEP, MCR4, POMC, and PCSK1." (PMID 33113859, 2020). "Diet-induced obesity has been shown to reduce mitochondrial Ca2+ accumulation capacity in POMC neurons, leading to greater levels of free intracellular Ca2+ which contributes in part to a reduction in POMC neuronal excitability by activation of hyperpolarizing Ca2+-activated K+ channels." (PMID 33240218, 2020). "Conversely, arcuate-specific or POMC neuron-specific overexpression of Socs3 leads to obesity." (PMID 33382813, 2020). "Moreover, ER–mitochondria contacts in POMC neurons of the hypothalamus were decreased in diet-induced obesity." (PMID 33339212, 2020). "Furthermore, the elevation of KATP channel activity induced by increased mTOR signaling leads to hypertrophy of POMC neuronal cells, eventually developing aging-dependent obesity." (PMID 33776740, 2020).